IDO1 (indoleamine 2,3-dioxygenase 1)
Diseases named in the same sentence as IDO1 in open-access papers (continued):
Sharing a sentence is not in itself a finding about the gene and the disease.
depression (continued). "Because IDO1 activity is closely related to Trp levels, the activation of IDO1 and the involvement of the immune system and inflammation in depression suggest that the inhibition of IDO1 could be a target for discovering antidepressant drugs." (PMID 36408235, 2022). "Considering that negative correlation between 5-HT and IDO1 has been associated with depression, it is imperative to note that the majority of the 5-HT-producing neurons in the CNS are located in the DRN." (PMID 33591947, 2021). "Considering that highly expressed IDO1 has been associated with depression, we next used Ido1-/- mice with or without CUMS administration to assess body weight and behavioural changes and TRP metabolism." (PMID 33591947, 2021). "As a consequence of these metabolic effects, it has been postulated that the activation of IDO1 may be responsible for some manifestations, like hyperalgesia, WP, and depression, which are frequently encountered in patients with pSS." (PMID 33572487, 2021). "Inflammatory stimuli mediated IDO1 hyper-activation also reduces the survival of serotonergic neurons along with marked microglial activation, another evidence of inflammatory mechanisms contributing to pathology of depression and neurodegeneration." (PMID 34205235, 2021). "Surprisingly, based on fMRI analysis, we also found that loss of IDO1 prevented the CUMS induced disorders of BOLD signals in hippocampus, suggesting that hippocampus might be the specific region regulated by IDO1 in depression." (PMID 33591947, 2021). "Some polymorphisms of the IDO1, 2 and KMO encoded genes are identified in patients with depression." (PMID 34072767, 2021). "Therefore, we selected the DRN as a target brain region to study the mechanisms through which IDO1 regulates depression." (PMID 33591947, 2021). "Furthermore, ablation of Ido1 exerted stress resistance and decreased the sensitivity of depression in CUMS mice with the stable BOLD signals, BDNF expression and neurogenesis in hippocampus." (PMID 33591947, 2021). "Our experimental results shown that deletion of IDO1 could effectively improve depression behaviour in the CUMS mice and indicated that IDO1 ablation could be a powerful method for controlling depression-related phenotypes." (PMID 33591947, 2021). "This rate-limiting enzyme is part of an inflammatory process thought to be taking part in depression development as this IDO1 mediates activation of pro-inflammatory cytokines and participated in the production of kynurenine and its metabolites in the brain hippocampus area." (PMID 32992963, 2020). "In this way, Zhou and his team’s work demonstrated on a mice population that peripheral indoleamine 2,3-dioxygenase 1 (IDO1) is implicated in depression-like behavior expression, but not involved in neuropathic pain." (PMID 32992963, 2020). "Based on the results of clinical and preclinical studies, it has been proposed that the switch from sickness to the cognitive/affective symptoms of depression is mediated by immune-dependent activation of the tryptophan metabolizing enzyme, indoleamine 2,3 dioxygenase (IDO1)." (PMID 30102966, 2018). "Importantly, these works suggest that overactivities of MAO-A and IDO-1 play an important pathophysiological role in the CORT-induced depression, which can be effectively counteracted by M30." (PMID 27870896, 2016). "Yet, it remains elusive the role of neuroinflammation and IDO-1 in CORT-induced depression." (PMID 27870896, 2016). "IDO1 has been proposed to lie at the interface between chronic inflammatory disease and depression." (PMID 27828964, 2016). "As a result, IDO1 controls and fine-tunes both innate and adaptive immune responses under a variety of conditions, including pregnancy, transplantation, infection, chronic inflammation, autoimmunity, neoplasia, and depression." (PMID 24533148, 2014).
depression (continued). "In conclusion, the results of the present study implicate hippocampal IDO1 activation in epilepsy-associated depressive-like behavior, suggesting that depression in TLE patients could be treated through the regulation of brain inflammation and IDO1 activity." (PMID 24594021, 2014). "Therefore, the regulation of the enzymatic activity of IDO1 is useful in the treatments of tumor, inflammatory diseases, and depression." (PMID 24533148, 2014). "To determine whether IDO1 activity is required for central LPS to induce depression-like behavior, we examined whether IDO1 KO mice or WT control mice develop depression-like behavior." (PMID 23866724, 2013). "Although additional experiments are necessary to fully determine the role that kynurenine metabolism plays in mediating the behavioral effects of inflammation, our data implicate IDO1 as an important component of central LPS-induced depression-like behavior, specifically sucrose preference." (PMID 23866724, 2013). "Depression-like behaviors may be differentially regulated by IDO1-dependent downstream kynurenine metabolism and proinflammatory cytokines; warranting further investigation into these possibilities." (PMID 23866724, 2013). "Even though it is generally accepted that IDO1 has significantly greater enzymatic activity and probably contributes the majority of increased kynurenine in our studies, our data suggest that an IDO1-independent pathway is responsible for depression-like behavior in the TST following ICV LPS." (PMID 23866724, 2013). "It is not clear as to which of these metabolites have a causative role in depression or if periphery or brain-generated tryptophan metabolites are responsible for depression-like behaviors but induction of peripheral or central IDO1 expression correlates with depression-like behavior of mice." (PMID 22189158, 2011). "Moreover, there is increasing evidence that the activation of the IDO1-driven Trp catabolic pathway has clinical implication for humans: shown for sepsis or trauma, depression and schizophrenia." (PMID 20689575, 2010). "Additionally, disturbances in the kynurenine pathway—where activation of IDO1 reduces the availability of tryptophan for serotonin synthesis—may contribute to depression." (PMID 40507778, 2025). "In our correlation analysis, IDO1 was positively correlated with the immobility time in the behaviour tests and negatively correlated with the E2 level in serum, indicating that IDO1 is likely to be involved in the pathomechanism of oestrogen withdrawal‐induced depression." (PMID 39467780, 2024). "Therefore, increased expression of IDO1 is an important feature of depression." (PMID 37190515, 2023). "As discussed in this review, targeting the production of immunopathic and potentially neurotoxic kynurenine metabolites by inhibitory downregulation of IDO-1 may prove a viable target against inflammation-induced neurological conditions, particularly depression and dementia." (PMID 37371332, 2023). "Accordingly, a new strategy for prevention and treatment of depression has emerged targeting inflammation (the pro-inflammatory cytokines and the pathways involved in their upregulation and overactivation) to ameliorate signs of depression through reducing IDO-1." (PMID 36781714, 2023). "Thus, inhibiting IDO1 may have therapeutic benefits for various diseases, such as, cancer, autoimmune disease, and depression." (PMID 36408235, 2022). "However, whether the EA modulates KP by inhibiting IDO1 improves depression-like behavior is unclear." (PMID 36703718, 2022). "Since there are different subtypes of depression, future investigation is warranted to test the more detail mechanisms of IDO1 in brain functional regulation and preclinical settings with human subjects and to validate the robustness of IDO1 intervention as a therapeutic strategy." (PMID 33591947, 2021).
depression (continued). "Notably, increased activity of indoleamine 2, 3 dioxygenase 1 (IDO1), the first and rate-limiting enzyme of the KYN pathway has been associated with diminished CNS 5-HT content, which is negatively correlated with the severity of depression symptoms." (PMID 33591947, 2021). "Therefore, we raise the possibility that potential therapeutic intervention for depression might be possible through targeting IDO1 activity, as an alternative to the current approach of symptomatic management with antidepressants." (PMID 33591947, 2021). "In addition to immunosuppressive Trp metabolites, cells expressing IDO1 may produce neuroactive Trp metabolites that exacerbate comorbidities such as pain, depression, and fatigue in patients with MS and other neuroinflammatory syndromes." (PMID 32625215, 2020). "On the contrary, the proceedings of Kim’s research demonstrated that by controlling hippocampal IDO1 through interleukine-6 it could be regulated depression-like behavior and also pain manifestations in rat models induced through persistent hind paw inflammatory pain." (PMID 32992963, 2020). "The development of depression-like behavior was dependent on stress-induced increases in circulating levels of kynurenine and could be treated by administration of Lactobacillus reuteri which down regulated IDO1 activity." (PMID 30102966, 2018). "Taken together, an alternative interpretation for the involvement of IDO1 in IFN-γ-induced depressive-like behavior may be that depression is related to not only the generation of neuroactive TRP metabolites but also the alteration of serotoninergic neurotransmission." (PMID 27436416, 2016). "IDO1 activity has been associated with decreased serotonin (5-HT) content and increased kynurenine (KYN) content and neuroplastic changes through the effect of KYN derivatives, such as quinolinic acid (QUIN), on glutamate receptors, which are all associated with depression." (PMID 24594021, 2014). "However, whether IDO1 activity within the brain is necessary for the manifestation of depression-like behavior of mice following a central immune challenge remains to be elucidated." (PMID 23866724, 2013). "Increased plasma KYN titres, due to IDO-1 over-expression, are a likely culprit due to KYN’s high BBB permeation and the correlation of CNS and plasma KYN titres, as well as the incidence of depression." (PMID 37371332, 2023). "In this study, BDNF+/−, IDO1−/−, and chronic ultra-mild stress (CUMS)-induced depression mouse models and controls were developed, and the differentially expressed genes were analyzed." (PMID 35711916, 2022). "In the poststroke depression (PSD) mouse model, 3-hydroxyanthranilate 3,4-dioxygenase (HAAO), QUIN, IDO1, Iba-1, and ROS were remarkably increased in the nucleus accumbens (NAc), HIP, and hypothalamus." (PMID 35668399, 2022). "Therefore, we hypothesize that DRN is potentially a brain area where IDO1 regulates depression." (PMID 33591947, 2021). "Curcumin, an IDO-1 inhibitor, suppresses NLRP3 expression in chronic unpredictable mild stress (CUMS) and reduces depression-like behaviors." (PMID 34735466, 2021). "The current findings from animal experiments suggest a novel mechanistic link between IDO1 in the DRN and depression, which the detrimental effects of IDO1 hyperactivity are likely mediated through a loss of hippocampal BDNF expression." (PMID 33591947, 2021). "Taken as a whole, these findings corroborate the notion that the Ido1-/- mice had the ability of resisting to the CUMS induced depression associated with hippocampus function and neurogenesis, suggesting that IDO1 may be a powerful target for controlling depression-related phenotypes." (PMID 33591947, 2021). "The present study investigated the effects of the chronic administration of venlafaxine on the expression and methylation status of Katl, Tph1/2, Ido1, Kmo and Kynu in the brain and blood of rats exposed to the CMS model of depression." (PMID 32406039, 2020).
depression (continued). "These cytokines influence depression-related pathophysiology by activating innate immune signaling pathways, including TLR4, NF-κB, MAPK, and the NLRP3 inflammasome, while also reshaping tryptophan-kynurenine metabolism through IDO1 and TDO2." (PMID 42212166, 2026). "The neurotransmitter hypothesis of depression at the transcriptomic level can be tested using BDNF- and IDO1-knockout mouse models and RNA-seq." (PMID 35711916, 2022). "In this study, we conducted WT and IDO1 mutant mice studies with functional magnetic resonance imaging (fMRI) analysis to confirm that IDO1 was the critical regulator in biochemical imbalances of TRP metabolites, and disorder of brain BOLD signals in the pathophysiology of depression." (PMID 33591947, 2021). "Our findings highlight an antidepressant effect by injection of IDO1 inhibitor into the DRN of mice and raise the possibility that IDO1 is involved in controlling depression in humans and may thus represent a novel drug target." (PMID 33591947, 2021). "In addition, a trend of increased KYN/TRP ratio, reflecting TRP breakdown to KYN (due to either activated IDO1, IDO2 or TDO), was found in the patients with major depression in comparison to the healthy controls (Mann–Whitney-U: 1338.0; p = 0.061)." (PMID 29109914, 2017). "In contrast, in the absence of Ido1 (knockout mice), inflammation-dependent depression-like behaviors are attenuated." (PMID 27799931, 2016). "We hypothesized that the high induction of IDO1 and the imbalance of TRP metabolites induced by IFNs in humans may be related to psychiatric side effects such as depression." (PMID 27436416, 2016). "Thus, IDO1 activation increases KYN derivatives and likely contributes to the comorbidity between epilepsy and depression." (PMID 24594021, 2014). "Other dioxygenases with activity similar to IDO1, such as TDO2 and possibly IDO2, could play a role in increasing kynurenine levels in response to central LPS treatment to precipitate certain depression-like behaviors." (PMID 23866724, 2013). "Evidence exists indicating that cytokines can influence depression-like behaviors independent of IDO1 expression." (PMID 23866724, 2013). "Taken together, these data indicate that inhibiting IDO1 with 1MT does not protect mice from the nonspecific sickness response; however, 1MT protected mice from the development of depression-like behavior following ICV LPS." (PMID 23866724, 2013). "These preclinical findings could warrant clinical investigations into the possibility of blocking 5-HT1A auto-receptors and/or IDO1 as a strategy to maintain the therapeutic effects of SSRI for the treatment of comorbid pain and depression in clinical settings." (PMID 36588734, 2022). "In contrast with these data supporting the relationship between the IFN pathway and WP/depression features, fatigue—which is present in around 70% of patients with pSS—did not appear to have relationship with the IFN signature, the related cytokine production, or IDO1 activation." (PMID 33572487, 2021). "Thus, IDO1 hyperactivity played crucial roles in modulating 5-HT metabolism and BDNF function thereby impacting outcomes of hippocampal neurogenesis and BOLD signals in depressive disorder." (PMID 33591947, 2021). "A recent study in a mouse model of middle cerebral artery occlusion demonstrated that the macrophages/microglia could enhance indoleamine 2,3-dioxygenase 1 (IDO1)-dependent neurotoxic kynurenine metabolism during ischemic pathogenesis, which was closely related to the post-stroke depression." (PMID 33192328, 2020). "However the respective role of peripheral and brain IDO1 in inflammation-induced depression-like behavior was not assessed in these studies." (PMID 23866724, 2013). "Moreover, there is evidence that inhibition of IDO1, TDO, and KMO or other interventions targeting Trp metabolism (like diet or probiotics) may further improve neurobehavioral manifestations including CRF or depression." (PMID 32153576, 2020).
depression (continued). "IDO1, TDO, KMO, and KAT inhibitors are also under investigation, mainly for cancer and not depression purposes." (PMID 35955633, 2022). "To determine whether activation of brain IDO1 is required for depression-like behavior, we selected a dose of LPS that, when administered ICV, has no measured effect on peripheral IDO1." (PMID 23866724, 2013).
glioma (135 papers, 2012 to 2026). A benign or malignant brain and spinal cord tumor that arises from glial cells (astrocytes, oligodendrocytes, ependymal cells). "The results revealed that CSF1R, TGFBI, and IDO1 serve as key nodes in the protein interaction network, suggesting their critical roles in glioma progression and tumor-associated inflammation." (PMID 40881678, 2025). "Here, we showed that the expression of IDO1 was markedly increased in patients with glioma and associated with GBM progression." (PMID 39863603, 2025). "IDO1 has been reported to be associated with angiogenesis, but the relationship between IDO1 and angiogenesis in glioma, as well as the mechanisms by which IDO1 regulates angiogenesis, require further investigation." (PMID 39065567, 2024). "For the first time, our study examined the association between IDO1 and glioma angiogenesis and the underlying mechanisms." (PMID 39065567, 2024). "It has been indicated that high IDO1 expression is linked with a poor outcome in GBM patients, and an IDO1 blockade with an IDO1 inhibitor Epacadostat (INCB024360) or Indoximod achieves good therapeutic efficacy in glioma-bearing mice." (PMID 39065567, 2024). "They found that other than IFN-γ, IFN-β also helps in increasing the expression of IDO-1 in glioma stem cells, causing treatment resistance." (PMID 37445721, 2023). "A recent systematic review and meta-analysis revealed that high expression of IDO1 was associated with poor prognosis in patients with various types of cancer including gliomas." (PMID 37152037, 2023). "For gliomas, upregulation of IDO-1 is associated with immune suppression and the patient usually shows a reduced survival rate." (PMID 37445721, 2023). "According to a recent, thorough investigation and meta-analysis, increased IDO1 expression was linked to poor prognosis in a variety of cancers, including glioma." (PMID 36146527, 2022). "Survival analysis using UALCAN shows that high expression of IDO-1 was often associated with worse prognosis, such as in low-grade glioma, papillary renal cancer, pancreatic cancer, endometrial cancer, and uveal melanoma." (PMID 34367262, 2021). "Previous studies have reported that PD‐L1, TIM‐3, and IDO1 transcriptional levels are highly associated with immune response and prognosis in patients with glioma." (PMID 32678519, 2020). "Together, our results showed that the IDO1/TDO–Kyn–AhR–AQP4 signaling pathway is a new mechanism underlying the malignancy of gliomas, and suggest that both IDO1 and TDO might be valuable therapeutic targets for gliomas." (PMID 32296044, 2020). "In addition, it was revealed that Kyn treatment promoted U87MG cell migration and invasion, and the decrease in glioma cell motility caused by IDO1 inhibition or TDO knockdown was restored when exogenous Kyn was supplemented." (PMID 32296044, 2020). "Although normally expressed at low levels in the CNS, IDO1 expression increases with glioma grade and is further upregulated by inflammatory stimuli." (PMID 40471422, 2025). "A significant increase in serum VEGFA concentration and tumor CD34 expression was observed in IDO1-overexpressing GL261 subcutaneous glioma-bearing mice." (PMID 39065567, 2024). "The effect of the KP blockade by IDO1 inhibitor RY103 on tumor angiogenesis was evaluated with GL261 subcutaneous glioma-bearing mice." (PMID 39065567, 2024). "Our research not only enhanced the understanding of the relationship between IDO1 and angiogenesis in glioma in terms of mechanism but also proposed the promising strategy of combining an IDO1 inhibitor with an angiogenesis inhibitor for glioma treatment." (PMID 39065567, 2024). "As a contributing factor to both angiogenesis and immunosuppression, several studies have shown the importance of IDO1 in glioma." (PMID 39065567, 2024).